LINC00276 (long independently transcribed non-coding RNA 276)
Synonyms: NCRNA00276
Gene: Long non-coding RNA gene on chromosome 2 (13,710,526 to 14,418,000, reverse strand). Ensembl gene ENSG00000230448.
Diseases named in the same sentence as LINC00276 in open-access papers:
LINC00276 is named in the same sentence as 2 diseases in open-access papers, as found by Europe PMC text mining. Sharing a sentence is not in itself a finding about the gene and the disease. The quoted sentences say what the papers report.
colorectal cancer (1 paper, 2024). A primary or metastatic malignant neoplasm that affects the colon or rectum. "LINC00276 plays a crucial role in cellular regulation and protein binding, highlighting its importance as a potential prognostic marker for colorectal cancer (CRC)." (PMID 38484366, 2024).
LINC00276 also shares sentences with these, for which no sentence is quoted: cancer (1 paper).